BCL6 (BCL6 transcription repressor)
Diseases named in the same sentence as BCL6 in open-access papers (continued):
Sharing a sentence is not in itself a finding about the gene and the disease.
lymphoma (continued). "Neoplastic cells in pcBCLf correspond to mature B lymphocytes (CD19+, CD20+, CD79a+, PAX-5+), which express markers of germinal center cells (BCL-6, CD10) and, in contrast to nodal centrofollicular lymphomas, are usually BCL2-." (PMID 36291756, 2022). "Lymphomas with rearrangements of MYC with BCL2 and/or BCL6 are called “double-hit lymphomas”(DHL) or “triple-hit lymphomas”(THL)." (PMID 35498426, 2022). "The lymphoma cells were positive for CD79a, PAX5, CD10 (diffuse), BCL‐6, MUM1, MYC, BCL‐2, CD3 (subset) and CD5 (subset), and negative for TdT and CD61, with a proliferation index of 80%." (PMID 36467806, 2022). "High‐grade B‐cell lymphomas with MYC and BCL2 and/or BCL6 rearrangements were rare in the NPS, which is clinically relevant because these lymphomas have a poor prognosis." (PMID 35104916, 2022). "Consistent with the development of an AITL condition, the transcriptome of the lymphoma samples obtained from Trp53ER/ER;Vav1ΔC/ΔC mice includes the upregulation of AITL‐specific genes such as Bcl6, Maf, Il21, Pdcd1, and Icos." (PMID 35895495, 2022). "These lymphomas are known as double-hit (DH) or triple-hit (TH) lymphomas and, in the 2017 WHO classification, they belong to the provisional category of High-grade B-cell lymphomas with MYC and BCL2 or BCL6 rearrangements, or both (HGBCL-DH/TH)." (PMID 35200580, 2022). "Sixty-four (45.4%) tumors showed a MYC rearrangement; 29 (20.57%) samples thereof had an additional BCL2 rearrangement (hence belonging to the DHL category); one lymphoma sample revealed translocations in MYC, BCL2, and BCL6 (THL)." (PMID 34830747, 2021). "In our current probe panel for lymphoma, we targeted the BCL2, BCL6, and MYC genes, bus also included the immunoglobulin loci IGH, IGK, IGL, and other loci implicated in hematolymphoid malignancies." (PMID 34099699, 2021). "In contrast, 28% of the patients with DLBCL presented BCL6 rearrangement, 25% presented c-MYC rearrangement, and 16% presented BCL2 rearrangement, with 16% presenting double-hit lymphomas." (PMID 34819573, 2021). "In the most recent WHO review of lymphoma classification, the DHL/THL category is now recognized as "high-grade B-cell lymphoma (HGBL) with rearrangements of MYC and Bcl-2 and/or Bcl-6." (PMID 33412518, 2021). "Regarding the baseline characteristics of the lymphomas, 70.8% of the tumors expressed MUM1, 65.2% expressed BCL2, and 72.7% expressed BCL6." (PMID 34782660, 2021). "Further, BCL6 expression has been shown to be unrestrained in some lymphomas, and it has been proposed that this mediates downregulation of PRDM1 and consequent cancer progression due to a dysregulated Blimp1-BCL6 axis." (PMID 35154079, 2021). "Triple‐hit lymphoma (THL), which is classified into high‐grade B‐cell lymphoma with rearrangements of MYC, BCL2 and BCL6, presents aggressive biological behaviour." (PMID 34698437, 2021). "The MALT-lymphomas showed enlarged meshworks of CD23(+) follicular dendritic cells colonized by CD20(+) Bcl2(+), Bcl6(−) and CD10(−) B lymphocytes." (PMID 33467055, 2021). "Patient 1 had a double-hit lymphoma with a MYC translocation and an additional BCL6 translocation and patient 5 had a triple hit lymphoma with additional BCL2 and BCL6 translocations." (PMID 33561953, 2021). "BCL6 and MYC rearrangements simultaneously occurred in case 8, which was diagnosed as “double hit” lymphoma." (PMID 34267187, 2021). "Twenty-eight percent of the patients with DLBCL presented BCL6 rearrangement, 25% presented c-MYC rearrangement, and 16% presented BCL2 rearrangement, with 16% presenting double-hit lymphomas." (PMID 34819573, 2021). "In the cases of DLBCLs, 3 triple expressor lymphoma cases and 7 double expressor lymphoma cases were identified by the co-expression of cMYC, BCL2, and BCL6 (cutoff points for expression of cMYC protein (≥ 40%), BCL2 protein (≥ 50%), BCL6 protein (≥ 50%))." (PMID 34737339, 2021).
lymphoma (continued). "Double- and triple-hit lymphomas are now defined as “high-grade B-cell lymphoma (HGBCL) with rearrangements of MYC and BCL2 and/or BCL6”, an entity separate from DLBCL in the 2016 revision of the World Health Organization lymphoma classification." (PMID 34945817, 2021). "Patients with ABC-DLBCL or genetic alterations in MYC and BCL2 and/or BCL6, called double hit (DHL) or triple hit lymphomas (THL), generally have a poor survival prognosis." (PMID 35008680, 2021). "In total, PLIER identified 137 rearrangements involving MYC, BCL2, and BCL6: 56 MYC rearrangements (in 49 lymphoma samples), 39 BCL2 rearrangements (in 34 samples), and 42 BCL6 rearrangements (in 40 samples)." (PMID 34099699, 2021). "Recent studies have identified that certain subpopulations of DLBCL and BL contain MYC, Bcl-2 and/or Bcl-6 translocations and were called “double hit” lymphoma (DHL) or “triple hit lymphoma” (THL)." (PMID 33412518, 2021). "Prior research revealed that due to the synergic effect of BCL6 and EZH2 in lymphoma, targeting BCL6 and EZH2 together leads to a great therapeutic effect." (PMID 31903129, 2020). "The ‘DH’ lymphomas are defined as a chromosomal breakpoint affecting the MYC/8q24 and another recurrent genetic abnormality, mainly involving BCL2, BCL6, BCL3 or other genes." (PMID 32459397, 2020). "A remarkable interplay has also been described between PRMT5 and the B cell lymphoma 6 (BCL6) oncogene during the lymphomagenesis in the GC, suggesting that pharmacological inhibition of arginine methylation could be of special interest in BCL6-driven lymphoma." (PMID 31681423, 2019). "Triple hit lymphomas harbor MYC, BCL-2, and BCL-6 rearrangements and have an aggressive clinical course and poor prognosis." (PMID 30718665, 2019). "In the most recent WHO revision of lymphoma classification, DHL/THL category is now recognized as "high-grade B cell lymphoma (HGBL) with rearrangements of MYC and BCL-2 and/or BCL-6." (PMID 31288832, 2019). "The 1E6A4 antibodies, recognizing the epitope BCL6235-350, will be useful for the detection of BCL6, which is significant in diagnosis of DLBCL or other GC-derived lymphoma." (PMID 31063496, 2019). "Thus, modulation of BCL6 expression could be a potential target for therapy in lymphomas." (PMID 31712669, 2019). "Knockdown of AIP in OC1-LY7 cells resulted in decreased AIP and BCL6 expression and decreased the viability of the DLBCL lymphoma cells." (PMID 31042473, 2019). "Double/triple-hit lymphomas (DHL/THL) account for 5–10% of diffuse large B cell lymphoma (DLBCL) with rearrangement of MYC and BCL2 and/or BCL6 resulting in MYC overexpression." (PMID 31288832, 2019). "Earlier studies reported that 5–15% of DLBCL harbored MYC, BLC2, and/or BCL6 translocations and were called “double-hit” lymphoma (DHL) or triple-hit lymphoma (THL)." (PMID 31288832, 2019). "For example, the boundaries of the antisense lncRNA RP11-211G3.3.1-1 from the BCL6 locus, precisely match the boundaries of the BCL6 translocation zone, and future studies should assess whether knockdown of this lncRNA could prevent BCL6 translocation and potentially preclude lymphoma development." (PMID 30134619, 2018). "“Double-hit” lymphoma (DHL) represents a subset of B-cell malignancies characterized by the presence of MYC (8q24) rearrangement and concurrent BCL2 (18q21) or BCL6 (3q27) rearrangements." (PMID 30323893, 2018). "In fact, BCL6 prevents MYC expression in the B-cells of the dark zone of the GC and adapts the cellular functions to the growth conditions of the lymphoma cells." (PMID 30038718, 2018). "“Double-hit” lymphoma (DHL) is a high-grade B-cell lymphoma that harbors concurrent MYC and BCL2 or BCL6 rearrangements." (PMID 30323893, 2018).
lymphoma (continued). "All these markers are essential to distinguish MZL from other types of lymphomas, such as CLL/SLL (CD5+ and CD23+), mantle cell lymphoma (CyclinD1+, CD5+, CD23−), and follicular lymphoma (CD10+ and Bcl6+)." (PMID 29740389, 2018). "Herein, we describe a fully characterized lymphoma cell line harboring simultaneous MYC and BCL6 rearrangements, designated DH-My6, that is proved to be immunophenotypically and genetically consistent with a primary DHL tumor." (PMID 30323893, 2018). "One of the major limitations in understanding the pathogenesis of MYC/BCL6 DHL is the lack of in vitro and in vivo models by which unlimited supplies of lymphoma cells with concurrent MYC and BCL6 rearrangements can be studied repeatedly and extensively." (PMID 30323893, 2018). "This category was called “double hit” lymphoma (DHL) or triple hit lymphoma and now is recognized as “high grade B-cell lymphoma (HGBL) with rearrangements of Myc and Bcl2 and/or Bcl6." (PMID 28147336, 2017). "These lymphomas belong to the new category called “High grade B cell lymphoma (HGBL), with rearrangements of MYC and BCL2 and/or BCL6”." (PMID 28375188, 2017). "The CD19 negative DLBCL were characterized further for other B cell lineage and lymphoma markers including CD20, PAX5, CD138, BCL2, BCL6, BCL10 and MUM1 using immunohistochemistry." (PMID 28484276, 2017). "MYC/BCL2 lymphomas were described as neoplasms with a phenotype characteristic of germinal center B cells: they express BCL6 and CD10, and lack IRF4, a regulator of BCL6." (PMID 28375188, 2017). "The large B-cell lymphomas with c-MYC and either BCL2 or BCL6 rearrangements are subsequently termed double-hit lymphomas (DHL), while those with all three rearrangements are referred to as triple-hit lymphomas (THL)." (PMID 28379189, 2017). "A worse outcome than double-expressor lymphomas show high grade B‐cell lymphomas (HGBL) with rearrangements of MYC and BCL2 and/or BCL6, the so-called double-hit or triple-hit lymphomas, which constitute a single category in the updated WHO classification." (PMID 29250206, 2017). "The second group, “MYC-complex” included lymphomas with IG-MYC fusions or non–IG-MYC fusions that have a high chromosomal complexity score (≥6), an IGH-BCL2 fusion, BCL6 breakpoint, or any combination of these." (PMID 28379189, 2017). "These “double-hit” or “triple-hit” lymphomas are included in the updated WHO classification in the category of high-grade B‐cell lymphoma (HGBL), with rearrangements of MYC and BCL2 and/or BCL6." (PMID 29250206, 2017). "MYC translocation was present in four of 26 (15%) evaluable cases, two of them had an additional BCL2 rearrangement (Double hit lymphoma) and one patient had additional BCL2 and BCL6 rearrangements (Triple hit lymphoma)." (PMID 27285986, 2016). "To test whether up-regulation of BCL2 and BCL-XL might cause lymphoma cells to become especially dependent on these pathways for survival in the absence of BCL6, we knocked down BCL6 in OCI-Ly1 cells as before and treated with the BCL2 and BCL-XL inhibitor ABT-737 250 nM for 72 h." (PMID 26657288, 2016). "Patients with both MYC and BCL2 CNA had similar outcomes to those with classic double hit lymphoma or protein double expression lymphoma (MYC and BCL2/BCL6 coexpression)." (PMID 26158410, 2015). "The term ‘double‐hit’ lymphoma was originally used to describe aggressive DLBCL with MYC and BCL2 translocation, then subsequently extended to include those with MYC and BCL6 translocation." (PMID 27347428, 2015). "A recently published comprehensive study of double-hit and triple-hit lymphomas showed that 62 % of double hit lymphomas involve BCL2 and 18 % involved BCL6, the remaining cases were triple-hit lymphomas." (PMID 26654227, 2015). "FISH analyses using BAC clones covering lymphoma breakpoints (BCL2, BCL6, BCL11A, CCND1, CCND3, IG-H/K/L, JAK2, LMO2, MYC, PAX5, REL) all tested normal, excluding rearrangements at these loci." (PMID 26599546, 2015).
lymphoma (continued). "Importantly, we compared the prognostic differences of double CNA with classic DHL and protein double expression (MYC and BCL2/BCL6 coexpression) lymphoma (DEL) and indicated the special value of double CNA which might be an important supplement to the DHL system." (PMID 26158410, 2015). "It was reported that MYC concurrent with BCL2 or/and BCL6 translocations in DLBCL, called double-hit lymphoma or triple-hit lymphoma (DHL/THL), determines highly aggressive clinical behavior with extremely poor outcome and resistance to chemotherapy." (PMID 26158410, 2015). "Patients with both MYC and BCL2 copy number aberration had similar outcomes to those with classic double-hit lymphoma (DHL) or protein double expression lymphoma (MYC and BCL2/BCL6 coexpression)." (PMID 26416427, 2015). "Most DH lymphomas had MYC and BCL2 gene translocations, whereas a small subset has MYC/BCL6 rearrangements." (PMID 26416427, 2015). "Understandably, we also observed the B-cell lymphoma protein (BCL6 and its paralog coding gene BCL6B) and other leukemia-related disease genes involved in lymphoma pathogenes, such as BCL11A." (PMID 25649207, 2014). "Immunophenotypically, these lymphomas often have a germinal center B-cell phenotype with positivity for CD10 and bcl6, and are frequently bcl2 positive." (PMID 25274079, 2014). "Double-hit (DH) and triple-hit (TH) lymphomas are transformed B-cell lymphomas that are generally defined by the presence of MYC gene rearrangement together with either BCL2 and/or BCL6 gene rearrangement." (PMID 24887414, 2014). "Interestingly, AID deficiency reduces the risk for development of Bcl6-dependent germinal center-derived lymphoma, while the loss of AID has no impact on Myc-driven, pre-germinal center lymphomas or on the progression of germinal center-like lymphomas in Msh6-deficient mice." (PMID 24212831, 2011). "Similar mechanisms account for other types of leukemia and lymphomas such as AML1-ETO and LAZ3/BCL6, respectively." (PMID 16248899, 2005). "Therefore, high expression of CD10 and BCL6 and lower MUM1 expression reflects the predominance of GCB-type differentiation in HIV-related lymphomas, as supported by previous studies." (PMID 40496610, 2025). "Conversely, cases are classified as the non-GCB subtype if lymphoma cells were CD10− Bcl6− or CD10− Bcl6 + MUM1+." (PMID 40365164, 2025). "High-risk molecular subtypes include DLBCLs with MYC and BCL2 and/or BCL6 rearrangements (“double-hit” or “triple-hit” lymphomas), now classified as high-grade B-cell lymphoma (HGBCL-DH/TH) by the World Health Organization." (PMID 41114812, 2025). "In lymphoma diagnostics, particularly for DLBCL and HGBCL, a Hi-C-based lymphoma assay enables diagnosis-agnostic detection of gene fusions of IGH::MYC and IGH::BCL2, and rearrangements of MYC, BCL2, and BCL6, in a single assay." (PMID 41010038, 2025). "Similarly, the double-expressor phenotype was also less prevalent in PT-DLBCL, while BCL6 rearrangements, double-expressor phenotype, and even double-hit lymphomas involving MYC and BCL6 or BCL2 are reported more frequently in western countries." (PMID 41244893, 2025). "Inhibiting BCL6-BTB will inhibit GC formation and lymphoma cell proliferation, without causing significant toxic side effects or macrophage-driven inflammatory responses." (PMID 39815148, 2025). "Currently, several strategies involving the combination of BCL6 inhibitors with several agents, including PRMT5 inhibitors, EZH2 inhibitors, STAT3 inhibitors and chemotherapy drug doxorubicin, have been explored for the treatment of lymphomas." (PMID 39815148, 2025).
lymphoma (continued). "Moreover, classifications that used to be under “Burkitt-like” lymphoma are now categorized as either high-grade B-cell lymphoma with MYC and BCL-2 and/or BCL-6 rearrangement, Burkitt-like lymphoma with 11q aberration, or simply high-grade B-cell lymphoma." (PMID 38535155, 2024). "Interestingly, in this category, there is a subset of cases, approximately 30%, in which the BCL6 gene is the MYC partner gene, and this group is termed pseudo-hit lymphoma." (PMID 39684922, 2024). "Nevertheless, the ΔEBNA2 + Myc lymphoma cells do not express the master regulator of GC differentiation, BCL6 and thus are not true GC B cells." (PMID 38620028, 2024). "Moreover, in human lymphoma cell lines, FBW7 expression levels are inversely correlated with BCL6 expression." (PMID 38485719, 2024). "A German high-grade lymphoma study group performed a post hoc analysis of DLBCL patients, treated in prospective clinical trials, regarding their COO and expression of MYC, BCL2, and BCL6." (PMID 38397877, 2024). "MCL may also gain secondary BCL2, BCL6, and MYC rearrangements, as proposed in three of the previously reported quadruple hit lymphomas." (PMID 38914869, 2024). "“Double hit” lymphomas with MYC and BCL2/BCL6 alterations confer a poor prognosis." (PMID 38534887, 2024). "Molecular pathology features: According to the European Neuro-Oncology Association guidelines for the diagnosis of immunocompetent primary lymphomas, the immunohistochemical features of diffuse large B-cell lymphoma of the central nervous system are marked by CD10, CD19, CD20, PAX-5, BCL-6, MUM1." (PMID 36961159, 2023). "Some studies have demonstrated the correlation of BCL6 and CD10 with MUM1 positivity in lymphoma." (PMID 37373354, 2023). "This category now consists of MYC and BCL2 rearranged cases exclusively, while the MYC/BCL6 double hit lymphomas now constitute genetic subtypes of DLBCL, not otherwise specified (NOS) or of HGBL, NOS." (PMID 37190213, 2023). "Peli1 expression positively correlates with the MYC, BCL6, BCL2, and MUM1 expression in lymphomas." (PMID 38179042, 2023). "It has been shown that higher grade lymphoma, especially FL3b, is different from lower grade FL in its cytogenetic and immunohistochemical profile such as BCL2, BCL6, MYC and IRF4, which may contribute to the development of a different TME." (PMID 37591873, 2023). "A unique group among high-grade lymphomas, characterized by specific gene rearrangements, these lymphomas carry translocations in MYC together with one, or both, of the anti-apoptotic proto-oncogenes, BCL2 and BCL6." (PMID 37958379, 2023). "Though double-hit-lymphomas and triple-hit-lymphomas are clinically aggressive neoplasms with poor prognosis, no significant clinical influence of the immunohistochemical assessment of c-Myc and BCL-2/BCL-6 was found in multivariate analyses." (PMID 36376836, 2022). "Additionally, three patients were diagnosed with double-hit lymphoma in the murinized group, carrying MYC and BCL2 or BCL6 translocations simultaneously, compared to four patients in the humanized group." (PMID 36552849, 2022). "Tumors developed in Faslpr/lpr mice were positive for BCL6, a marker generally expressed by human GC-related DLBCLs, whereas lymphomas developed in absence of OPN were negative for this marker." (PMID 36503430, 2022). "These so-called “double-hit” or “triple-hit” (DH/TH) lymphomas have been included in the 2016 updated WHO classification in the new category of high-grade B cell lymphoma (HGBL) with rearrangements of MYC and BCL2 and/or BCL6." (PMID 35060000, 2022).